VDR (vitamin D receptor)
Description:
Nuclear receptor for calcitriol, the active form of vitamin D3 which mediates the action of this vitamin on cells. Enters the nucleus upon vitamin D3 binding where it forms heterodimers with the retinoid X receptor/RXR. The VDR-RXR heterodimers bind to specific response elements on DNA and activate the transcription of vitamin D3-responsive target genes. Plays a central role in calcium homeostasis (By similarity). Also functions as a receptor for the secondary bile acid lithocholic acid (LCA) and its metabolites.
Synonyms: NR1I1; PPP1R163
Tractability: Small molecule: an approved drug acts on it; a structure with a bound ligand is known; a high-quality ligand is known; it has a high-quality binding pocket; it belongs to a druggable protein family. PROTAC: UniProt records ubiquitination sites on it; ubiquitination databases record sites on it; a small molecule that binds it is known.
Target class: Nuclear receptor; Transcription factor; Nuclear hormone receptor subfamily 1; Nuclear hormone receptor subfamily 1 group I; Nuclear hormone receptor subfamily 1 group I member 1
Chemical probes: LG190178, PD081520
Safety:
Unwanted effects reported when the protein is acted on. In parentheses: how it was acted on, where the effect was seen, and who reports it.
anemia (source: ClinPGx)
Gene: Protein-coding gene on chromosome 12 (47,841,537 to 47,943,048, reverse strand). Ensembl gene ENSG00000111424.
Subcellular location: Nucleus; Cytoplasm
Subcellular location (Human Protein Atlas): Nucleoplasm; Cytosol; Intermediate filaments
Pathways (Reactome):
Gene expression (Transcription): Nuclear Receptor transcription pathway
Metabolism: Vitamin D (calciferol) metabolism
Metabolism of proteins: SUMOylation of intracellular receptors
Gene Ontology:
Molecular function: bile acid nuclear receptor activity; calcitriol binding; DNA binding; DNA-binding transcription factor activity; lithocholic acid binding; nuclear receptor activity; nuclear retinoid X receptor binding; protein binding; vitamin D response element binding; DNA-binding transcription factor activity, RNA polymerase II-specific; nuclear steroid receptor activity; RNA polymerase II cis-regulatory region sequence-specific DNA binding; vitamin D binding; sequence-specific DNA binding; zinc ion binding
Biological process: cell morphogenesis; decidualization; mRNA transcription by RNA polymerase II; negative regulation of cell population proliferation; negative regulation of DNA-templated transcription; negative regulation of keratinocyte proliferation; negative regulation of transcription by RNA polymerase II; nuclear receptor-mediated bile acid signaling pathway; phosphate ion transmembrane transport; positive regulation of gene expression; positive regulation of keratinocyte differentiation; positive regulation of transcription by RNA polymerase II; positive regulation of vitamin D receptor signaling pathway; response to bile acid; retinoic acid receptor signaling pathway; vitamin D receptor signaling pathway; cell differentiation; intracellular receptor signaling pathway; positive regulation of bone mineralization; vitamin D metabolic process; cellular response to vitamin D; nuclear receptor-mediated steroid hormone signaling pathway; regulation of DNA-templated transcription
Cellular component: chromatin; cytoplasm; nucleoplasm; nucleus; receptor complex; RNA polymerase II transcription regulator complex
Genetic constraint (gnomAD): Loss-of-function variants: 19 observed, 39.06 expected, observed/expected ratio (o/e) 0.49, 90% interval 0.34 to 0.71. The upper end of that interval is the gene's LOEUF score, 0.71, which puts it in group 2 of 6, group 1 being the genes least tolerant of losing a copy. Missense variants: 442 observed, 587.85 expected, observed/expected ratio (o/e) 0.75, 90% interval 0.69 to 0.81. Synonymous variants: 242 observed, 222.99 expected, observed/expected ratio (o/e) 1.09, 90% interval 0.98 to 1.21.
Homologues: Orthologues: chimpanzee VDR (100% identical), macaque VDR (98% identical), dog VDR (93% identical), pig VDR (92% identical), rat Vdr (90% identical), mouse Vdr (88% identical), guinea pig VDR (87% identical), tropical clawed frog vdr (75% identical), rabbit VDR (71% identical), zebrafish vdrb (70% identical), zebrafish vdra (41% identical), zebrafish vdra (28% identical), and 183 more. Paralogues in human: NR1I2 (41% identical), NR1I3 (33% identical), NR1H3 (30% identical), NR1H4 (28% identical), NR1H2 (28% identical), NR1D2 (26% identical), THRB (26% identical), NR1D1 (24% identical), PPARG (24% identical), RARA (24% identical), RARB (24% identical), PPARD (23% identical), and 6 more.
Diseases named in the same sentence as VDR in open-access papers:
VDR is named in the same sentence as 733 diseases in open-access papers, as found by Europe PMC text mining. Sharing a sentence is not in itself a finding about the gene and the disease. The quoted sentences say what the papers report.
vitamin D deficiency (444 papers, 2008 to 2026). A nutritional condition produced by a deficiency of VITAMIN D in the diet, insufficient production of vitamin D in the skin, inadequate absorption of vitamin D from the diet, or abnormal conversion of vitamin D to its bioactive metabolites. "Intestinal diseases like inflammatory bowel disease, intestinal failure, and irritable bowel syndrome have also been linked to vitamin D deficiency and VDR expression." (PMID 42232580, 2026). "Growing evidence links vitamin D deficiency and vitamin D receptor (VDR) gene polymorphisms to pregnancy complications, including RPL." (PMID 42274468, 2026). "This review focuses on the gastrointestinal tract, with high VDR content and known associations between vitamin D deficiency and disease states." (PMID 42232580, 2026). "While VDR functionality is crucial for hair follicle maintenance, the relationship between vitamin D deficiency and hair loss presents a complex picture." (PMID 41473843, 2026). "Vitamin D deficiency and genetic variations in the vitamin D receptor (VDR) gene are important factors influencing bone health, yet their combined effects remain insufficiently studied, particularly in North African populations." (PMID 42193110, 2026). "Vitamin D deficiency has also been linked to impaired skeletal muscle performance through VDR-mediated pathways and mitochondrial dysfunction, contributing to muscle weakness and reduced physical function." (PMID 41470808, 2025). "Conversely, vitamin D deficiency or impaired VDR function can disrupt keratinocyte maturation and compromise barrier integrity, potentially contributing to inflammatory skin conditions." (PMID 40943440, 2025). "Many studies have shown that vitamin D deficiency and vitamin D receptor TaqI gene polymorphisms are associated with susceptibility to diabetic nephropathy in various populations." (PMID 40575263, 2025). "Reported associations between CYP2R1, GC, and VDR gene variants and the risk of vitamin D deficiency." (PMID 41340975, 2025). "For VDR polymorphisms, the risk allele associated with vitamin D deficiency is the C allele for ApaI and TaqI." (PMID 41340975, 2025). "Pathogenic Mechanism: Vitamin D deficiency (25(OH)D <20 ng/mL) disrupts VDR-mediated Treg/Th17 balance, increasing anti-TPO titers by 40–60% and hypothyroidism progression risk." (PMID 40822954, 2025). "This study provides novel insights into the role of active vitamin D (1,25(OH)2D3) and its receptor (VDR) in uterine biology, offering evidence that vitamin D deficiency impairs uterine function and that VDR regulates endometrial stromal cell differentiation." (PMID 41292920, 2025). "Vitamin D deficiency influences the microbiome composition and integrity of the gut epithelial barrier, primarily through the vitamin D receptor (VDR)." (PMID 39996823, 2025). "The exploration of the mechanism in this study only focused on inflammatory indicators, without involving neurotransmitters (such as serotonin, BDNF) and VDR gene polymorphisms, and the sample only covered people with vitamin D deficiency." (PMID 40821024, 2025). "In excitatory neurons, we found vitamin D receptor pathway downregulated, Figure-5 (a), and vitamin D deficiency has been linked to AD and other neurodegenerative diseases." (PMID 41282152, 2025). "The A/A genotype of VDR FokI showed a statistically significant association with vitamin D insufficiency in the codominant model (G/G vs. G/A vs. A/A, OR = 8.90, 95% CI = 1.80–43.97, p < 0.01)." (PMID 41156448, 2025). "In endometriosis, VDR expression is upregulated in both eutopic and ectopic endometrium, and vitamin D deficiency has been identified as playing a significant role in disease pathogenesis." (PMID 41394244, 2025). "In conclusion, vitamin D deficiency causes abnormal levels of cholesterol and its derivatives via VDR mediated transcriptional regulation of the expression of HMGCR." (PMID 40276652, 2025).
vitamin D deficiency (continued). "Studies using animal models investigating the role of the vitamin D receptor in fertility and reproductive function reveal that vitamin D deficiency reduces female fertility by inducing uterine developmental defects." (PMID 41195173, 2025). "Recently, studies have also implicated vitamin D deficiency, as well as vitamin D receptor gene (FokI, BsmI, TaqI) polymorphism in the increased risk of developing both DM and MM." (PMID 40620564, 2025). "The A/A genotype of the VDR FokI polymorphism (rs2228570) showed a strong correlation with vitamin D insufficiency (G/G-G/A vs. A/A, OR = 9.25, 95% CI = 2.01–42.51, p < 0.01) but not deficiency." (PMID 41156448, 2025). "This review explores the role of vitamin D deficiency and differences in vitamin D receptor density in the regulation of the immune system and immune responses in Hashimoto’s thyroiditis, considering future directions." (PMID 41226614, 2025). "While serum vitamin D deficiency has consistently been linked to poorer recovery trajectories, fewer investigations have examined genetic variation within the VDR gene as an additional layer of biological modulation." (PMID 41227071, 2025). "Vitamin D deficiency leads to the suppression of vitamin D receptor (VDR) function, directly downregulating the expression of sex hormone synthases, thereby reducing the production of testosterone and estradiol." (PMID 40352262, 2025). "Given the importance of vitamin D and VDR polymorphisms in persistent post–renal–transplant hyperparathyroidism, and the high prevalence of vitamin D deficiency after KT, vitamin D supplementation is particularly important following renal transplantation." (PMID 41036144, 2025). "Combined analysis of serum vitamin D levels and VDR genetic variants suggests a link between vitamin D deficiency, VDR mutations, and susceptibility to chronic HF." (PMID 41438090, 2025). "Many studies have shown that vitamin D deficiency and vitamin D receptor TaqI gene polymorphisms are associated with susceptibility to diabetic retinopathy in various populations." (PMID 40264687, 2025). "The objective of this study was to determine the impact of vitamin D deficiency and vitamin D receptor TaqI gene polymorphism on the risk of diabetic retinopathy complications in T2DM at the Debre Tabor Comprehensive Specialized Hospital, Northwest Ethiopia." (PMID 40264687, 2025). "Second, we were unable to further explore the causative links between VDR, vitamin D deficiency or free 25(OH)D levels and GDM because pertinent SNPs were not available." (PMID 39203740, 2024). "Conditions involving VDR knockout and vitamin D deficiency appear to imply detrimental effects on the homeostasis of skeletal muscle." (PMID 39599698, 2024). "Vitamin D deficiency and type 2 diabetes mellitus are risk factors for colorectal cancer, suggesting a role for vitamin D receptor (VDR) and insulin receptor (INSR) gene polymorphisms." (PMID 39201651, 2024). "Specifically, vitamin D deficiency caused by a polymorphism in the vitamin D receptor (VDR) gene is associated with lower levels of serum vitamin D in children with ASD, when compared with controls." (PMID 39596221, 2024). "Combined with the known profibrotic effects of impaired VDR signaling in stellate cells, the studies provide a mechanism whereby vitamin D deficiency would both reduce hepatocyte proliferation and permit fibrosis, leading to significant liver compromise." (PMID 38963813, 2024). "This study aimed to investigate the association between diabetes with vitamin D deficiency and the VDR gene variant (FokI), which is related to the binding of vitamin D to its receptor." (PMID 38812030, 2024). "This study aimed to explore the potential association between vitamin D deficiency and anxiety and depression symptoms in adults, considering the role of the vitamin D receptor gene polymorphism FokI (rs2228570)." (PMID 38519539, 2024).
vitamin D deficiency (continued). "Several SNVs in the VDR gene have been associated with metabolic disorders and vitamin D deficiency to date, including rs1544410 (BsmI), rs7975232 (ApaI), and rs731236 (TaqI)." (PMID 38530345, 2024). "The aim of the current review is to comprehensively examine and elucidate the relationship between vitamin D deficiency and the vitamin D-vitamin D receptor (VDR) axis in the context of MASLD pathogenesis and progression." (PMID 38732118, 2024). "The authors found that neonates born to mothers with the VDR rs2228570 GG genotype and with vitamin D deficiency had significantly larger head circumferences." (PMID 38613027, 2024). "Vitamin D deficiency is associated with reduced expression of the Vitamin D receptor and epithelial barrier proteins E-cadherin and claudin-2, which play an important role in children with CD in correlation with histological manifestations of disease severity." (PMID 38491474, 2024). "Unavoidably, in a vitamin D deficiency/D treatment model, all the cells in the animal are affected by vitamin D, preventing the delineation of the role of VDR in hepatocytes on liver regeneration vs other cell types." (PMID 38963813, 2024). "Among the susceptibility factors that have been studied in ISPTB but never reached unambiguous conclusions on causative association is vitamin D deficiency and the potential role of vitamin D receptor (VDR) gene variants." (PMID 39519264, 2024). "We have earlier reported low maternal vitamin D status in both preeclamptic and normal pregnancies, warranting further evaluation of the influence of vitamin D deficiency and VDR gene variants on women experiencing PE." (PMID 38814968, 2024). "In conclusion, this study indicates a possible genetic predisposition indicated by VDR polymorphisms associated with vitamin D deficiency in the etiology of prosthesis loosening." (PMID 39125794, 2024). "Previous studies have reported that TB susceptibility can be caused by vitamin D deficiency, which is affected by polymorphisms in the vitamin D receptor (VDR) gene." (PMID 39228416, 2024). "Vitamin D deficiency, VDR, or CYP27B1 depletion has been shown to cause an increase in Mycobacterium anisopliae and Mycobacterium avium, triggering epithelial barrier dysfunction and intestinal inflammation." (PMID 38549749, 2024). "Compared with men, female are more likely to suffer from vitamin D deficiency due to the enhancement of vitamin D receptor gene expression and transcription by estrogen." (PMID 38652023, 2024). "In cases where the VDR gene exhibits reduced responsiveness, this can result in a manifestation of vitamin D deficiency." (PMID 39451780, 2024). "To decipher the effects of vitamin D deficiency on cardiac function, we generated a cardiomyocyte-specific VDR knockout mouse model using Cre-LoxP technology." (PMID 38892126, 2024). "Doxercalciferol, a vitamin D receptor agonist, highlights the close association between vitamin D deficiency and conditions such as diabetes, arterial hypertension, and chronic kidney disease." (PMID 38715799, 2024). "Vitamin D deficiency will stimulate the activation of the VDR in adipocytes and negatively affect the energy metabolism, which subsequently predisposes to obesity." (PMID 37242192, 2023). "Previous studies reported that vitamin D deficiency was associated with a decrease in the concentration of vitamin D receptors (VDR) and that the level of VDR was negatively correlated with SOFA score and lactate and C-reactive protein levels." (PMID 37892385, 2023). "Another study (cross-sectional with 277 patients) assessed the associations between vitamin D deficiency, VDR gene polymorphisms (ApaI, BsmI, FokI, and TaqI), and cardiovascular risk factors in T2DM Caribbean patients." (PMID 36839157, 2023). "For this reason, we investigated the influence of 25 OH vitamin D deficiency and of SNPs in genes implicated in vitamin D metabolism (VDR and CYP24A1) on lipid parameters." (PMID 37632926, 2023).